RN7SL284P (RNA, 7SL, cytoplasmic 284, pseudogene)
Gene: Miscellaneous RNA gene on chromosome 10 (77,912,271 to 77,912,545, reverse strand). Ensembl gene ENSG00000243446.
Homologues: Orthologues: chimpanzee Metazoa_SRP (97% identical), macaque Metazoa_SRP (91% identical). Paralogues in human: RN7SL2 (85% identical), RN7SL1 (85% identical), RN7SL3 (84% identical), RN7SL769P (83% identical), RN7SL788P (83% identical), RN7SL218P (82% identical), RN7SL301P (82% identical), RN7SL786P (82% identical), Metazoa_SRP (81% identical), RN7SL125P (81% identical), RN7SL278P (81% identical), RN7SL627P (81% identical), and 706 more.